MTOR (mechanistic target of rapamycin kinase)
Diseases named in the same sentence as MTOR in open-access papers (continued):
Sharing a sentence is not in itself a finding about the gene and the disease.
metabolic disorders (continued). "In the Web of Science database, hundreds of articles have focused on the effect of mTOR signaling on the progression of CRC through cellular physiology, metabolic disorders, and mTOR components." (PMID 39723045, 2024). "Our results reveal a previously unrecognized metabolic disorder in conjunction with aberrant PI3K/AKT/mTOR signaling that contributes to platelet hyperreactivity in MPN patients." (PMID 38060311, 2024). "Other aspects of metabolic diseases have also been explored where mTOR has been shown to be central." (PMID 38892329, 2024). "Prospectively, abnormalities in PI3K/AKT pathway can be suggestive of cascade activation of mTOR implicating its potential in exaggerating inflammatory response in metabolic disease." (PMID 38711460, 2024). "Illuminating the relationships between mTOR and furin is vital for future therapeutic interventions in metabolic disorders." (PMID 37830621, 2023). "Despite T2D being extensively studied and the well-established role of mTOR signaling in metabolic diseases, the role of PCs (including furin) in the mTOR signaling pathway has been rarely explored." (PMID 37830621, 2023). "We found the metabolic pathways associated with endocrine and metabolic disease, the endocrine system, carbohydrate metabolism, signal transduction, and energy metabolism were upregulated in ICP (except mTOR signaling pathway)." (PMID 38260149, 2023). "It was reported that HIF-1 (a gene involved in the pathogenesis of metabolic disorders) expression is increased due to increased PKM2 expression via the PI3K/mTOR pathway." (PMID 37516743, 2023). "The mTOR signaling pathway modulates fundamental cellular processes, and its dysregulation contributes to the pathogenesis of tumors, metabolic diseases, neurodegeneration, and aging." (PMID 36986146, 2023). "For instance, OS causes metabolic disorders by affecting the regulation of PPARα, AMPK/mTOR, and SIRT3/FOXO3a." (PMID 35784531, 2022). "This includes efforts to translate mTOR regulation as a therapeutic for neurological disorders, metabolic disease, and skeletal health." (PMID 36586433, 2022). "However, it remains to be eludicated whether these associations are causal (e.g., via mTOR activation) or consequential (e.g., due to reduced mitochondrial oxidation) in metabolic disease, and whether UPF intake plays a role in the etiology of the association of BCAAs with metabolic health." (PMID 35076016, 2022). "Food restriction activated adenosine monophosphate-activated protein kinase, which then inhibited and suppressed mTOR signaling to slow aging and increase resistance to pathologies, including metabolic diseases." (PMID 34557073, 2021). "The AMPK/mTOR signaling pathway is a master regulator of metabolism and critically involved in metabolic diseases." (PMID 32884949, 2020). "More basic and clinical studies are required to better understand the beneficial and side effects of mTOR inhibiting strategy against metabolic disorders." (PMID 30011848, 2018). "We will also briefly discuss the therapeutic potential of mTOR signaling for the metabolic disorders." (PMID 30011848, 2018). "For instance, the 5′-adenosine monophosphate-activated protein kinase (AMPK) and mammalian/mechanistic target of rapamycin (mTOR) signaling play significant roles in the development of these metabolic disorders." (PMID 29116185, 2017). "Although mechanisms through which rapamycin impacts on regulatory cells is still elusive, the present study however extends the concept that targeting the mTOR signaling pathway deserves interest in the treatment of metabolic diseases." (PMID 24710396, 2014). "Given the key position of mTOR at the crossroads of several hormonal and nutrient signalling pathways regulating food intake and energy homeostasis, this kinase might constitute a major gatekeeper system underlying the developmental programming of metabolic disorders." (PMID 24040371, 2013).
metabolic disorders (continued). "In OA, chondrocytes stress upregulate IGF1R in an attempt to repair, but sustained activation induces excessive PI3K mTOR signaling, which accelerates chondrocyte metabolic disorders, aging, and apoptosis, and promotes synovial vascular opacities to invade cartilage." (PMID 41261625, 2025). "The literature suggests that MTOR is related to metabolic disorders and immune function, further suggesting that STAT3 may contribute to the occurrence of long-term amenorrhea through these mechanisms." (PMID 40137514, 2025). "Collectively, mTOR signaling is highly influential in the regulation of cell metabolism and, as such, has emerged as a prominent molecular target in preventing and treating metabolic disease." (PMID 38999929, 2024). "Another study on high‐fat diet (HFD)‐fed mice demonstrated that TRF improved the mTOR pathway function without reducing calorie intake, maintained glucose homeostasis and anabolism in the liver, and partially reversed the metabolic disorders caused by HFD." (PMID 36776765, 2023). "Although FoxOs and Sestrins have been extensively studied for their involvement in metabolic diseases; however, how FoxOs-Sestrin-mTOR cascade participates in metabolic regulation and diseases is still largely unknown." (PMID 36942499, 2023). "Moreover, Sesn2 can activate the AMPK pathway and suppress mTOR signaling to attenuate various metabolic disorders, including insulin resistance, mitochondrial dysfunction, and cardiac dysfunction." (PMID 36133815, 2022). "Herein, we found that mTOR is involved in ROS-related energy metabolism disorders." (PMID 35915740, 2022). "Moreover, pieces of evidence have shown that inhibition of the mTOR signaling pathway by some drugs can delay the development of metabolic diseases." (PMID 36428983, 2022). "Phosphoinositide 3-kinase (PI3K) and AKT, a serine/threonine protein kinase also known as protein kinase B, are key components with the mechanistic target of rapamycin (mTOR) for signaling network, possibly related to the pathogenesis of cardio-metabolic disorders." (PMID 36671395, 2022). "Pharmacological inhibition of mTOR by rapamycin would have a wide range of clinical effects, so it can benefit patients with tumors while the use of rapamycin monotherapy in a broad spectrum of metabolic diseases is limited due to its modest efficacy." (PMID 35949314, 2022). "As TBK1 and mTOR contribute to tumorigenesis and metabolic disorders, these kinases may work together in a direct manner in a variety of physiological and pathological settings." (PMID 34245780, 2021). "However, TRF/E may contribute to the prevention of metabolic diseases via modulation of the Clock–Bmal1 pathway, synchronizing hormonal signals, regulating the Sirt1 pathway, inhibiting mTOR signaling, and modulating gut-microbiome-related nutrient-sensors." (PMID 36678130, 2023). "However, how FoxOs-Sestrins-mTOR cascade participates in the cellular metabolism and metabolic diseases remains largely unknown." (PMID 36942499, 2023). "Given that changes in mTOR activity also influence the incidence of metabolic disease at an individual level, regulatory links between the proteasome and mTOR might be therapeutic targets for metabolic disorders." (PMID 36834633, 2023). "In metabolic disorders, such as atherosclerosis, the PI3K/Akt and mTOR pathways are also pivotal in regulating autophagy." (PMID 40001518, 2025). "For instance, pea protein hydrolysate alleviates GDM-related metabolic disorders and placental dysfunction by inhibiting the PI3K/AKT/mTOR/PPARγ signaling pathway." (PMID 41460830, 2025). "In CML, autophagy supports leukemic stem cell survival and TKI resistance by leveraging the same mTOR, PI3K/Akt, and AMPK pathways, which are also critical in the pathogenesis of neurodegenerative and metabolic disorders." (PMID 40001518, 2025).
metabolic disorders (continued). "Another example of T–B interactions is given in the context of inflammation and metabolic disorders, with a crosstalk between the central axis of the PI3K/Akt/mTOR pathways and the redox homeostasis integrated in the mitochondria." (PMID 38500390, 2024). "HFD also disrupts normal cellular metabolic programming and perturbs the activities of the regulators of nutrient homeostasis, including mTOR, AMPK, and CREB, which contribute to metabolic diseases." (PMID 37492592, 2023). "Studies have shown that PI3K/AKT/mTOR, AMP-activated protein kinase (AMPK), MAPK, SIRT1, FoXO, signalling pathways are important in the regulation of autophagy as well as cell aging and metabolic disorders." (PMID 36994671, 2023). "Studies have demonstrated the significance of the signalling pathways PI3K/AKT/mTOR, AMP-activated protein kinase (AMPK), MAPK, SIRT1, and FoXO in the control of autophagy, cell aging, and metabolic diseases." (PMID 36994671, 2023). "According to recent studies, Sestrin2 plays a crucial role in metabolic disorders of cardiovascular events, such as oxidative stress, AMPK/mTOR ignalling pathway, and Nrf2-induced autophagy." (PMID 35729499, 2022). "Thus, exploring the effects of BCAA on mTOR and insulin signaling in SAT might provide new perspectives on the nutritional management of dairy cows during periods when they are most susceptible to metabolic disorders." (PMID 34573680, 2021). "We provide a rationale for therapeutic mTOR modulation to prevent exhaustion of the regenerating MSC pool and to protect from vascular calcification due to age and metabolic diseases." (PMID 31882658, 2019). "Collectively, these findings suggest that ATM may alleviate inflammation and metabolic disorders in T2DM by modulating gut microbial composition, elevating SCFA levels, and activating the AMPK/mTOR pathway." (PMID 40046742, 2025). "Similarly, studies on metabolic disorders, such as on the impact of microcystin-LR on liver lipid metabolism via the PI3K/AKT/mTOR/SREBP1 signalling pathway, demonstrate the critical role of oxidative stress and lipid regulation in pathological conditions." (PMID 40104582, 2025). "In the context of metabolic disorders, studies suggest that melatonin restores the activity of the PI3K/AKT/mechanistic target of rapamycin (mTOR) pathway, reduces insulin receptor substrate-1 (IRS-1) phosphorylation, and increases insulin-like growth factor 1 (IGF-1) activity." (PMID 40722923, 2025). "Remarkably, a critical feature of the metabolic disorders for ACLF was the disruption of lipid and fatty acid metabolism, manifesting as the upregulation of genes related to the peroxisome proliferator-activated receptor (PPAR) and mTOR signaling pathways." (PMID 37380987, 2023). "Moreover, mTOR, PI3K-Akt, and AMPK signaling pathways play unique roles in the regulation of T cells, which provide a new direction for the treatment of metabolic diseases in the future." (PMID 36428983, 2022). "However, compared with healthy patients receiving insulin stimulation, the expression of mTOR protein in the corpus luteum of PCOS patients is less, so another link between PCOS and mTOR is metabolic disorders during PCOS." (PMID 32785222, 2020). "The activation of MTOR regulates various effector functions of CD4+ and CD8+ T cells, and MTOR inhibitors (i.e., rapamycin) are used as potential immunosuppressive therapeutics for organ transplants, metabolic diseases, and various autoimmune disorders." (PMID 30469437, 2018). "Therefore, the mTOR inhibitor rapamycin, an FDA-approved drug for patients with organ transplant has been considered for treatment of metabolic disorders." (PMID 24710396, 2014). "By targeting mTOR, SIRT1 and other pivotal molecules, immune metabolic dual regulatory natural products can synchronously regulate immune response and metabolic activities, and block the vicious cycle of immune activation, metabolic disorder and vascular remodeling." (PMID 41585867, 2025).
metabolic disorders (continued). "The mechanisms underlying the protective effects of resveratrol on various cardiovascular and metabolic disorders have not been established; however, evidence suggests that the inhibition of the mammalian target of rapamycin (mTOR) signaling pathway could play a role." (PMID 24489988, 2013).
neurological disorders (153 papers, 2010 to 2025). "The dysregulation of the mTOR pathway can have profound consequences, leading to abnormal neurodevelopment and metabolic disturbances, which are linked to a group of neurological disorders known as mTORopathies." (PMID 40358185, 2025). "Neurological disorders caused by genetic defects within the mTOR pathway are called mTORopathies and are characterized by malformations in the cerebral cortex, epileptogenesis, cognitive impairment and autism." (PMID 39652154, 2024). "Due to critical biological roles of mTOR in vivo, its deficient signaling causes a diverse group of neurological disorders, termed ‘mTORopathies’." (PMID 36675042, 2023). "mTOR has key functions in nervous system development and mis-regulation of mTOR signaling causes aberrant neurodevelopment and neurological diseases, collectively called mTORopathies." (PMID 36226315, 2022). "Hoeffer collected substantial evidence that mTOR signaling is associated with synaptic changes, memory, and neurological disorders." (PMID 36118114, 2022). "The deregulation of mTOR signaling appears to be a common hallmark of human neurological disorders, including PD37, and mTORC1-induced transcripts enriched in a cluster of genes related to PD38." (PMID 34504106, 2021). "In regard to the mTOR pathway, mTOR is a 289-kDa serine/threonine protein kinase and is vital during nervous system disease and memory loss." (PMID 34590471, 2021). "REDD1 is closely associated with neurological diseases because mTOR is a crucial protein that regulates synapse formation and plasticity." (PMID 33322202, 2020). "Impaired mTOR activity has been associated with neurological disorders and neurodegenerative diseases." (PMID 32051464, 2020). "In contrast, studies have demonstrated that moderate reduction of mTOR activity by ~25%–30% consistently improves aspects of brain function in models of aging and of age‐associated neurological disease." (PMID 31693798, 2020). "Activation and inflammatory responses of SH-SY5Y cells are usually associated with the PI3K/mTOR/GSK3β signaling pathways, which in turn trigger a range of neurological diseases, such as hypothalamic inflammation, AD, and PD." (PMID 32832542, 2020). "While aberrant changes in mTOR signaling are associated with sensitization of the pain pathway (sensory neurons and spinal cord), there are various nervous system diseases that have pain as a comorbidity and altered mTOR activity in the brain." (PMID 31194026, 2018). "To date, the majority of neurological disorders associated with mTOR signaling have been linked to mTORC1." (PMID 28335463, 2017). "Two established genetic mechanisms through which mTOR signaling abnormalities lead to neurological disease are mutations that disrupt the Pten or Tsc1 genes." (PMID 24574959, 2014). "In the brain, hyperactivation of mTOR signaling causes neurological disorders in both humans and in animal models." (PMID 24574959, 2014). "An emerging treatment for a diverse range of neurological disorders associated with neurodegeneration is rapamycin, a key modulator of the mammalian target of rapamycin (mTOR) pathway." (PMID 23861877, 2013). "Altogether, the authors demonstrated that exosomes could serve as potential therapies in the management/treatment of other neurological diseases via regulating PI3K/Akt/mTOR and associated signaling pathways." (PMID 36986865, 2023). "The emerging pieces of evidence have revealed that the constitutive activation of the mTOR pathway due to mutations/amplification/deletion in either mTOR and its complexes (mTORC1 and mTORC2) or upstream targets is responsible for aging, neurological diseases, and human malignancies." (PMID 37779156, 2023). "Aberrant mTOR signaling causes a diverse group of neurological disorders, termed ‘mTORopathies’." (PMID 36675042, 2023). "Deregulation of mTOR is linked to several neurological diseases, including ASD." (PMID 33809910, 2021).